EGFR (epidermal growth factor receptor)
Diseases named in the same sentence as EGFR in open-access papers (continued):
Sharing a sentence is not in itself a finding about the gene and the disease.
cancer (continued). "EREG enhances glycolysis through activating EGFR signaling and its downstream glycolytic genes in tamoxifen-resistant BCa cells, whereby EREG is a direct target of miR-186-3p, downregulation of which by tamoxifen causes EREG upregulation in these cancer cells." (PMID 36202915, 2022). "In the current manuscript, we systematically evaluate the functional significance of putative fusion oncogenes as drug resistance mechanisms in EGFR mutant cancers using both preclinical models and patients treated with single agent EGFR inhibitors and/or combination therapies." (PMID 36153311, 2022). "Studies have shown that miR-134-5p significantly inhibited the expression of EGFR in cancer cells." (PMID 35236250, 2022). "As our data and prior studies suggest, EGFR-AMPK can regulate both of these cancer cell phenotypes." (PMID 36130485, 2022). "Other than EGFR+ cancer cells, there are noticeable cell clusters that are unique to GBM." (PMID 35624211, 2022). "EGFR is a receptor tyrosine kinase involved in multiple cancers." (PMID 35211652, 2022). "However, adaptive reliance on redundant pathways to overcome EGFR inhibition has been proposed in line with observations in other cancers treated with EGFR inhibitors." (PMID 36012105, 2022). "Among them, CET coating can target the epidermal growth factor receptor (EGFR) overexpressed on the surface of cancer cells and realize the local PTT and the release of chemotherapy drugs under the irradiation of NIR, thus avoiding the toxic and side effects on normal tissues." (PMID 36212064, 2022). "Along this line of speculation, it would be difficult to use erlotinib for validating the involvement of the EGFR-ProT-NF-κB-HOTAIR signaling axis in cisplatin-induced cancer cachexia in mice." (PMID 36471329, 2022). "Hence, the results of this study suggest that patients with high body weight should be carefully monitored for the development of acneiform rash when receiving anti-EGFR antibody drugs as cancer drug therapy." (PMID 36045384, 2022). "Their report had excluded patients who underwent RT, other anti-cancer drugs, or bone-modifying agents but crucially, had not accounted for the presence of EGFR mutations." (PMID 36581856, 2022). "In addition to its role in cancer cells, EGFR is expressed on several immune cells, including macrophages, monocytes, plasma cells, and Tregs." (PMID 36439487, 2022). "Targeting EGFR with specific inhibitors, antibodies, or vaccines has been extensively explored and recognized as useful strategies for therapeutic treatment against cancers." (PMID 35931120, 2022). "Furthermore, epidermal growth factor receptor (EGFR), one of the most important upstream targets of the MAPK/ERK pathway, is reported to be closely linked to cancer progression." (PMID 35382893, 2022). "A wide range of HER3 membrane expressions was observed in the clinical activity and Patritumab Deruxtecan could be an approach to treat a broad range of drug-resistant tumors due to clinical activity in EGFR-TKI resistant cancers." (PMID 36551663, 2022). "Clinical imaging performance using a fluorescent antibody was compared across 3 cancers to elucidate physical and biologic factors contributing to differential translation of epidermal growth factor receptor (EGFR) expression to macroscopic fluorescence in tumors." (PMID 35332092, 2022). "Interestingly, paired t-test analysis results show that the expression of EGFR was significantly reduced in the second cancer tissue." (PMID 35222283, 2022). "Specifically, in some studies, cancer cells harboring EGFR mutations seemed to have a higher level of EpCAM expression, supporting the strategy of using the current panel to isolate CTC for EGFR mutational testing in our study." (PMID 36142574, 2022). "Upregulation of EGFR has been demonstrated in many cancer types." (PMID 34991599, 2022).
cancer (continued). "Aberrant activation of the EGFR pathway axis has been found to play a major role in cancer." (PMID 35402265, 2022). "As such, EGFR-targeted therapies hold significant potential for the cure of cancers." (PMID 35213974, 2022). "Combining the RNA-seq results, we hypothesized that DNAJB11 induced EGFR/RAF/MAPK signaling to promote cancer cell growth." (PMID 36209075, 2022). "CAR-T therapy targeting EGFR is in early clinical development for numerous types of cancer." (PMID 36185288, 2022). "Cancer cells show increased expression of genes encoding fatty acid synthase (FASN), which correlates with resistance to anticancer drugs targeting the epidermal growth factor receptor (EGFR)." (PMID 36569285, 2022). "Gefitinib blocks EGF-mediated EGFR autophosphorylation in many EGFR-expressing cancer cells." (PMID 35402265, 2022). "In addition, HeLa, MG-63, and MCF-7 cancer cells, which have low EGFR overexpression compared to normal cells, took up the B-ASO compound at similar, low levels." (PMID 36499115, 2022). "In addition, high DSG2 expression was also reported to promote cancer cell growth and migration, and decrease the response sensitivity to EGFR targeting therapy in NSCLC cancer cells." (PMID 35345582, 2022). "Enrichment pathways analysis with target genes of top 10 bEV miRNAs demonstrated that cancer, epidermal growth factor receptor (EGFR), prolactin signaling pathway, erythroblastic leukemia viral oncogene homologue (ErbB), and forkhead box, class O (FoxO) signaling pathways are enriched." (PMID 36313069, 2022). "Deregulated EGFR signaling has a central role in driving cancer pathogenesis." (PMID 35931120, 2022). "Therefore, tyrosine kinase inhibitors that target mutated EGFR have been developed for treating NSCLC, as well as other cancers." (PMID 35745617, 2022). "Phototoxicity has been correlated to the level of EGFR expression in different cancer cell lines." (PMID 35213974, 2022). "In the case of spinal metastasis, several radiogenomics models in patients with primary lung malignancy have the ability to predict the presence or absence of the EGFR mutation through the analysis of MR images of the spine." (PMID 36011018, 2022). "This compound increases HIFα hydroxylation and thus subsequent targeting for proteosomal degradation, reduces VEGF expression and angiogenesis in both in vitro and in vivo cancer models as well as showing combination efficacy with the epidermal growth factor receptor (EGFR) receptor gefitinib." (PMID 36320041, 2022). "EGFR biomarker detection in oral squamous cell carcinoma may fulfil multiple roles in cancer diagnostics, not only for early detection, but also at diagnosis for prognostic evaluation and treatment." (PMID 35681586, 2022). "EGFR mutations are detected in 20%-40% of NSCLC patients and promote cancer progression." (PMID 35154464, 2022). "Besides, anti-CD3 was used to target CD3 on T cells and anti-epidermal growth factor receptor (EGFR) to target EGFR on cancer cells." (PMID 36185609, 2022). "EVs with EGFR-VII, EGFR, PDPN, and IDH1 secreted by spongioblastoma have been isolated, confirming that detection of circulating EVs predicts the clinical drug efficacy and cancer mutations." (PMID 36407096, 2022). "Overall, depletion of STYK1 from cancer cells may diminish persistence mechanisms elicited by EGFR inhibition, such as FGF1 upregulation, and in that way reduce/eliminate the pool of drug tolerant cells in which constitutive, genomic resistance may arise." (PMID 35840561, 2022). "It is worth mentioning that none of these studies have developed dual or multiple kinase inhibitors, in addition they have not evaluated the biological activity against EGFR-mutated cancer cell lines." (PMID 36000167, 2022).
cancer (continued). "First-generation (Erlotinib and Gefitinib) and second-generation (Dacomitinib and Afatinib) EGFR-TKIs are used to treat cancers harboring L858R and Ex19Del; T790M is observed usually in cancers that have acquired drug resistance due to selective pressure during clinical care." (PMID 35664805, 2022). "Aberrant EGFR signaling in cancer cells promotes the formation of actin-rich protrusions, called invadopodia, and increases cell motility and invasion during metastatic growth, suggesting that secreted EGF ligands may act as chemoattractants." (PMID 34982813, 2022). "The most important features were the cancer stage, size, age of diagnosis, smoking, and EGFR gene." (PMID 36428655, 2022). "Eight studies performed sequencing through different cancer‐related gene panels, and nine studies sequenced only predesignated genes including EGFR, KRAS proto‐oncogene (KRAS), B‐Raf proto‐oncogene (BRAF), erb‐b2 receptor tyrosine kinase 2 (ERBB2), and MET proto‐oncogene (MET)." (PMID 36000927, 2022). "EGFR overexpression has been involved in multiple cancers, including NSCLC." (PMID 35402265, 2022). "Epidermal growth factor receptor (EGFR) is closely related to carcinogenesis of different cancers." (PMID 35517789, 2022). "However, studies show that cancer cells undergo infinite proliferation, and cancer cells with a epidermal growth factor receptor (EGFR) wild-type is resistant to chemotherapy drugs; thus, there are few cancer cells which execute apoptosis or autophagy." (PMID 36467499, 2022). "Therefore, many researchers are developing cancer treatments targeting EGFR, K-Ras, Ras-downstream effectors, and EphA2." (PMID 35668076, 2022). "EGFR acts as an indirect transcription regulator: although it does not contain any DNA-binding site, it was reported to stimulate the transcription of different cancer promoting genes." (PMID 35954311, 2022). "Furthermore, EGFR is over-expressed in various human cancers including lung, breast, head, neck, colon and rectum." (PMID 35120180, 2022). "The conflict in the results from bulk and specific cell population also includes the study of epidermal growth factor (EGFR) that plays a critical role in many cancer types, with its downstream pathways including RAS-MAPK/PI3K-AKT-mTOR pathways that are well studied in cancer prognosis." (PMID 36498893, 2022). "These unique ‘loose’ binding characteristics of EREG with EGFR might facilitate its binding with LepR, increasing glucose influx in normal and/or cancer cells." (PMID 35159237, 2022). "In contrast, the non-mutation group mainly used EGFR as the primary driver gene to promote the occurrence and development of cancer." (PMID 36290362, 2022). "Epidermal growth factor receptor inhibitors have typically been used for treatment of cancer." (PMID 35911532, 2022). "After three months of anti-cancer treatment, we did not detect any EGFR mutations in the CTC samples due to no CTC detected." (PMID 36142574, 2022). "Currently, EGFR is one of the most well-known therapeutic targets in various cancers." (PMID 35628495, 2022). "EGFR is frequently overexpressed in a variety of tumors, and activating mutations of EGFR, RAS, and RAF are the most significant oncogenic drivers in many malignancies, including lung, colorectal, pancreatic, and skin cancers." (PMID 36438567, 2022). "From a mechanistical point of view, a chemical inhibition of growth factor-driven proliferation and an induction of cellular differentiation may be of interest for the treatment of EGFR-positive cancers." (PMID 34991250, 2022). "STAT3 is also a downstream cellular mediator of cancer and angiogenesis, induced by IL-6 and EGFR." (PMID 36145523, 2022). "Our EGFR immunohistochemistry results revealed the scale-dependent and multifactorial nature of biomarker expression, reflecting its intrinsic intratumoral and interpatient heterogeneity across cancers." (PMID 35332092, 2022).
cancer (continued). "The depletion of alveolar macrophages may indeed increase the availability of RBCEVs, thus improving the efficiency of EGFR‐VHH‐coated immRNA‐loaded RBCEVs to target EGFR‐positive cancer cells in the lung parenchyma." (PMID 35430766, 2022). "Curcumin inhibits EGFR signaling and reduces EGFR expression in cancer cells." (PMID 35977996, 2022). "Several landmark studies have suggested that when cancer cells are subjected to therapeutic pressure during anti-EGFR therapy, they acquire secondary genetic alterations in a process known as clonal evolution, which may contribute to drug resistance." (PMID 36248993, 2022). "These transitions parallel a breakdown of the BBB and an explosive growth of EGFR+ cancer cells." (PMID 35624211, 2022). "The combination of a miR-200-mimic and inhibitor of EGFR signaling might enhance the sensitivity of cancer cells to EGFR-TKIs." (PMID 35682560, 2022). "Recently, many studies have analyzed DElncRNAs in normal and LUAD tissues and have shown that LINC00460 is closely related to the progression of many types of diseases including cancer, which may become a new therapeutic strategy for EGFR-mutant LUAD." (PMID 36091160, 2022). "Anti-EGFR monoclonal antibodies conjugated MR contrast, F-18 labeled Affibody protein, C-11 erlotinib, Lu-177 nimotuzumab, or C-11 labeled 4-N-(3-bromoanilino)-6, 7-dimethoxyquinazoline, have been developed to target the EGFR of cancer." (PMID 35120180, 2022). "Furthermore, the bioactive compounds were predicted using GC-MS, which served as ligands for in silico molecular docking of the lung cancer receptor EGFR." (PMID 36358188, 2022). "Hence, coupling of CPT to these peptides did not interfere with CPT cytotoxic effects, while contributing a specific targeting tool to EGFR and EGFRvIII overexpressed cancer cell lines." (PMID 35890400, 2022). "Furthermore, the activation of EGFR signaling can upregulate the production of VEGF in human cancer cells, and EGFR and VEGF share a common downstream pathway, suggesting an important role of VEGF in resistance to EGFR-TKIs." (PMID 35650550, 2022). "Genomic aberrations in oncogenes such as epidermal growth factor receptor (EGFR) mutations and anaplastic lymphoma kinase (ALK) fusions have defined different molecular subtypes of NSCLC with unique cancer biology and response to matched tyrosine kinase inhibitors (TKI)." (PMID 35159091, 2022). "•CBD and CBG significantly induce cancer cells apoptosis in EGFR-positive cell A431." (PMID 36568260, 2022). "Notably, the acquisition of cancer stem-like properties contributes to EGFR-TKI resistance in NSCLC cells." (PMID 35301287, 2022). "TKIs block EGFR activation, inducing apoptosis in cancer cells addicted to EGFR signals." (PMID 35158954, 2022). "Our study virtually predicts anti-cancer activity for cocoa affected by hirsutrin inhibiting EGFR." (PMID 35421091, 2022). "In addition, KEGG pathways analysis suggests that this network is enriched in pathways including the JAK-STAT signaling pathway, PD-L1 expression and PD-1 checkpoint pathway in cancer, and EGFR tyrosine kinase inhibitor resistance." (PMID 35299868, 2022). "The enrichment of C6 analysis showed that the low expression of DIAPHs in PAAD of TCGA cohort was associated with genes downregulated by KRAS overexpression in cancer cell lines, whereas the high expression of DIAPH3 was associated with several oncogenes, such as E2F and EGFR." (PMID 36589226, 2022). "Both the results of WES and panel sequencing that covered the whole exome of 733 cancer-related genes showed lower TMB levels in NSCLC patients with than in those without EGFR mutations." (PMID 35265073, 2022). "Therefore, inducing EGFR degradation will beneficial for the treatment of EGFR high-expressing cancer patients." (PMID 35614042, 2022).
cancer (continued). "Analogously, to improve the selectivity of photosensitizer accumulation in EGFR-overexpressing cancer cells, chlorin e6 (Ce6) was conjugated with 4-arylaminoquinazolines, a class of molecules analogues to Vandetanib, a known tyrosine kinase inhibitor of both VEGFR-2 and EGFR." (PMID 35213974, 2022). "Additionally, GPCR ligands such as prostaglandins, bradykinin, and gastrin-releasing peptide can also transactivate EGFR to promote cancer cell proliferation, survival, and invasion." (PMID 35409206, 2022). "Therefore, a combination treatment that includes an Ephexin1-specific inhibitor and targeted inhibitors of EGFR, EphA2, or K-Ras is predicted to improve the effectiveness of cancer treatment." (PMID 35668076, 2022). "To investigate the effect of EGFR pathway inhibition on EGFR clustering, we imaged the transfected SW620 cells in the presence of EGFR pathway inhibitors cetuximab or trastuzumab, two commonly used anti-cancer drugs, which separately target EGFR and HER2, respectively." (PMID 35612280, 2022). "To evaluate the role of CD109/EGFR in the maintenance of the cancer stem cell population, we examined the self-renewal property of control A431, CD109-KO, CD109KOEGFR, CD109-KOCD109G, CD109-KOCD109S, or CD109KOEGFR+CD109G cells using an in vitro spheroid formation assay." (PMID 35954339, 2022). "Moreover, we have described a new unexpected link between EGFR dependency and methionine metabolism gene expression in cancer cell lines." (PMID 36361596, 2022). "Numerous signaling molecules lie downstream of EGFR involved in cancer development." (PMID 35402265, 2022). "In addition, a previously characterized antisense oligonucleotide with high metallacarboranes (FESANs) decoration was used to assess its lipofectamine-free cellular uptake in various normal and cancer cells, including those after EGFR silencing." (PMID 36499115, 2022). "EGFR SMIs have been approved worldwide for the treatment of multiple cancers." (PMID 35402265, 2022). "The EGFR represents an important receptor in cancer biology." (PMID 35216384, 2022). "A study thought that GALNT2 may promote cancer progression via activating EGFR/PI3K/Akt/mTOR pathway." (PMID 36060650, 2022). "It has been reported that EphA2 binds to EGFR in human cancer cell lines." (PMID 35668076, 2022). "Furthermore, EGFR has been reported to be involved in the development of multiple cancer types, including EC." (PMID 36117773, 2022). "Together, our study shows that HD6 may compete with EGF to bind to EGFR and interrupt cancer progression in CRC." (PMID 34975297, 2022). "JAK/STAT, VEGF and EGF/EGFR-mediated pathways are primarily involved in developmental stages but, interestingly, deregulation of these pathways has been widely documented during different stages of cancer." (PMID 36615262, 2022). "EGFR is regulated by miR-1-3p, and this interaction was already found in cancer." (PMID 35011725, 2022). "As a standard method of calculation, we suggest including both synonymous and non-synonymous somatic mutations without excluding mutations or genes associated with cancer (e.g. EGFR)." (PMID 36155654, 2022). "IL-6 has been shown to promote survival of transformed cholangiocytes through a number of pathways, including the p38 and p44/42 MAPK pathway and through DNA methylation of the promoter region of target genes involved in cancer growth, such as the epidermal growth factor receptor (EGFR)." (PMID 35565248, 2022).